GDF15 (growth differentiation factor 15)
Diseases named in the same sentence as GDF15 in open-access papers (continued):
Sharing a sentence is not in itself a finding about the gene and the disease.
Obesity (continued). "Moreover, AF frequently coexists with comorbidities such as hypertension, diabetes, and obesity, which exacerbate inflammatory and oxidative stress pathways, elevating GDF-15 levels." (PMID 41180477, 2025). "For children, GDF15 elevations appear to be associated with microvascular and intrahepatic changes related to obesity, but there was not a direct relationship observed between paediatric obesity and GDF15." (PMID 40019842, 2025). "Given the rising global prevalence of obesity and its economic and health burdens—particularly in older adults with limited treatment options—the observed increase in GDF-15 following combined exercise in this study suggests a meaningful correlation with weight and fat mass reduction." (PMID 40725674, 2025). "To date, GDF15 has been known to regulate inflammatory processes, apoptosis, angiogenesis, and cell growth and repair and was reported to play key roles in regulating body energy-related biological reactions, such as obesity and metabolic diseases." (PMID 40142684, 2025). "GDF15 has been discussed as potential biomarker or even pathophysiological key player in various neurological diseases, mitochondrial diseases, neuro-inflammation, metabolic stress activation, pregnancy-induced nausea, and obesity/weight regulation." (PMID 40820083, 2025). "CIN-109 is a long-acting analog of GDF15 for the treatment of obesity." (PMID 40837873, 2025). "Therapeutically, GDF15 is a strong candidate for a treatment option against obesity." (PMID 41034527, 2025). "In contrast, in overt diabetes or long‐standing obesity, high levels of GDF‐15 and disrupted signalling pathways may blunt the acute response of this adipokine to exercise stimuli." (PMID 41208056, 2025). "GDF15 levels increase significantly in patients with obesity and normoglycemia and in those with obesity and impaired glucose tolerance or type 2 diabetes, while FGF21 concentrations significantly decrease in patients with obesity and impaired glucose tolerance or type 2 diabetes." (PMID 40377893, 2025). "Targeting GDF15 has emerged as a potential therapeutic strategy for obesity and T2D." (PMID 40629349, 2025). "Consequently, plasma concentrations of GDF15 are elevated in various conditions such as aging, obesity, cancer, cardiovascular disease, and autoimmune diseases." (PMID 40351551, 2025). "The discovery of the GDF15-GFRAL axis in 2017 opened new therapeutic avenues for obesity treatment." (PMID 41204286, 2025). "While murine models highlight hepatic and adipose origins during metabolic stress, human data reveal paradoxes—notably the absence of obesity-associated GDF15 mRNA up-regulation in adipose tissue despite elevated systemic levels." (PMID 40837873, 2025). "Inhibition of GDF15/GFRAL signalling by genetic ablation of GFRAL or tissue-specific knockdown of GDF15 abrogates the anti-obesity effect of artesunate in mice with diet-induced obesity, suggesting that artesunate controls bodyweight and appetite in a GDF15/GFRAL signalling-dependent manner." (PMID 38310105, 2024). "It is unclear whether these observations are influenced by underlying metabolic stress and inflammation, which are characteristic of obesity, given the nature of GDF15 as a mitokine." (PMID 38762719, 2024). "The role of GDF15 in obesity remains obscure and is possibly different between humans and animals." (PMID 38762719, 2024). "Recent preclinical and clinical studies have highlighted that targeting the GDF15‐GFRAL signalling pathway is a promising approach for treating obesity, particularly because it has minimal impact on skeletal muscle mass, which is essential to preserve during weight loss." (PMID 39700016, 2024). "In addition to artesunate, other pharmacological GDF15 inducers, including camptothecin and metformin, have been shown to confer anti-obesity effects with comparable efficacies." (PMID 38310105, 2024).
Obesity (continued). "Whether elevated plasma concentrations of GDF15 are beneficial or detrimental in obesity and other illnesses still needs further investigation." (PMID 39700016, 2024). "GDF-15 circulating levels have been consistently found to be elevated in obesity." (PMID 39000420, 2024). "To further confirm whether the anti-obesity effect of artesunate is mediated by the GDF15/GFRAL axis, we quantified the percentage abundance of active c-Fos+ neurons within the AP, following a bolus intraperitoneal dose of artesunate." (PMID 38310105, 2024). "Although our current study points toward an effect of liraglutide on weight loss independent of GDF15, the concept of GDF15 as a potential treatment strategy for people living with obesity remains intriguing." (PMID 38965822, 2024). "Additionally, we will discuss recent advances and potential challenges in targeting the GDF15‐GFRAL axis for obesity treatment." (PMID 39700016, 2024). "Future experimental studies should also investigate the mechanisms involved in obesity-induced GDF-15 release by muscle cells and how adipocytes may contribute to the GDF-15 release." (PMID 39310722, 2024). "We first examined the level of serum GDF15 in mice with diet-induced obesity and normal mice." (PMID 38310105, 2024). "This is probably similar to fibroblast growth factor 21 (FGF21) and growth differentiation factor 15 (GDF15), whose endogenous expression and circulating levels are elevated in obese humans and mice despite their beneficial effects on obesity and related metabolic complications." (PMID 39436790, 2024). "However, further research is needed to elucidate how GDF15 influences other metabolic indicators and what role it plays in the pathogenesis of obesity." (PMID 39700016, 2024). "In patients with obesity and type 2 diabetes mellitus, elevated GDF15 was found." (PMID 38474863, 2024). "Summary of the drugs targeting GDF15‐GFRAL pathway in obesity." (PMID 39700016, 2024). "Moreover, patients with detectable preoperative levels of GDF15 had significantly lower body mass index and a lower prevalence of obesity compared to those with undetectable preoperative levels." (PMID 39766300, 2024). "Our study indicates that GDF‐15 increases in individuals with obesity in response to a 60 min MICT exercise session which may have contributed to the suppression of subjective appetite." (PMID 39263536, 2024). "Moreover, GDF15 which been positively associated with NAFLD-NASH progression, was increased in children with obesity of MASLD or MetS and leptin increased only in subjects of MASLD but not MetS." (PMID 39227971, 2024). "Clinical trials involving individuals with overweight and obesity who were treated with a long‐acting GDF15 receptor analogue showed a reduction in food intake and body weight, supporting the weight‐reducing effect of GDF15." (PMID 38965822, 2024). "GDF15 is a well‐known biomarker for metabolic diseases, with higher GDF15 levels corresponding to metabolic diseases such as atherosclerosis, cardiomyopathies, obesity, insulin resistance, and chronic kidney diseases." (PMID 38965822, 2024). "In our cohort, elevated GDF-15 was observed in mothers with a healthy BMI compared to those with overweight or obesity which suggests that this marker may be important to consider in future studies of metabolic conditions such as gestational diabetes." (PMID 38992196, 2024). "Furthermore, in subjects with obesity, bariatric surgery was shown to increase the plasma levels of GDF15 and insulin sensitivity, suggesting a possible positive role of GDF15 on insulin activity in humans." (PMID 38668314, 2024). "Brain-derived neurotrophic factor (BDNF), secreted protein acidic and rich in cysteine (SPARC), fibroblast growth factor 21 (FGF-21), growth differentiation factor 15 (GDF-15) are examples of such cytokines which have therapeutic potential in obesity and metabolic diseases." (PMID 37436597, 2023).
Obesity (continued). "The third candidate is GFRAL, which is required for the anti-obesity effects of GDF-15." (PMID 38254638, 2023). "An extended GDF15 exposure might occur due to high serum levels in different diseases including obesity and cancer as well as in aging." (PMID 37373159, 2023). "The obesity-related disease is a chronic inflammatory status, in which the compensatory protective effect of elevated GDF-15 might be due to its anti-inflammatory role, but eventually futile." (PMID 37152921, 2023). "Adipose tissue and immune cells entering the liver and adipose tissue in the process of developing obesity may abundantly express the GDF-15." (PMID 36927409, 2023). "In addition, the GFRAL gene was identified in 2005, and it has not been extensively studied until recently because of its important role in the anti-obesity effect of GDF-15." (PMID 38254638, 2023). "Therefore, in addition to being simply a cell/tissue stress-induced cytokine, it is plausible that the role of higher levels of GDF-15 in obesity and diabetes is to prevent progressive weight gain and to play a role in reducing inflammation." (PMID 37436597, 2023). "Indeed, recombinant GDF15 and its analogs reduce food intake and body weight and improve glucose intolerance in animal models of obesity." (PMID 37513338, 2023). "Furthermore, pharmacological administration of FGF21 or GDF15 ameliorates obesity and related metabolic complications by improving energy and glucose homeostasis." (PMID 37818094, 2023). "In humans, increases in GDF15 are seen with metformin-induced weight loss and exercise training, suggesting that higher circulating GDF15 levels linked to metabolic disease are not causative, but rather because of the metabolic stress from obesity and NAFLD." (PMID 37686725, 2023). "Treatment of rodents fed a high-fat diet with recombinant growth differentiating factor 15 (GDF15) reduces obesity and improves glycaemic control through glial-cell-derived neurotrophic factor family receptor α-like (GFRAL)-dependent suppression of food intake." (PMID 37380764, 2023). "While interesting for the treatment of obesity‐related pathologies, the appetite‐ and metabolism‐regulating properties of both GDF15 and FGF21 may be dangerous in cachexia." (PMID 36642986, 2023). "GDF15, therefore, represents an attractive target to combat the current global obesity epidemic." (PMID 36992609, 2023). "Indeed, systemic overexpression of GDF15 prevents obesity and insulin resistance by modulating metabolic activity and enhancing the expression of thermogenic and lipolytic genes in BAT and WAT." (PMID 37819027, 2023). "However, GDF15 levels are markedly elevated in various pathological conditions including cancer, inflammatory diseases, cardiovascular disease, obesity and mitochondrial dysfunction." (PMID 37818094, 2023). "Therefore, pharmacological modulation of endogenous GDF15 levels by small molecules offers promise for the treatment of obesity and T2DM." (PMID 37513338, 2023). "Additionally, there is mounting evidence that GDF-15 is involved in the pathophysiology of a number of metabolic disorders, including obesity-related insulin resistance and nonalcoholic fatty liver disease (NAFLD)." (PMID 36864452, 2023). "Several human genetic studies have assessed the link between GDF15 and obesity." (PMID 36992609, 2023). "Safe administration with limitation of nausea and vomiting remains a concern, but the development of an effective GDF15 analogue with reduced side effects could represent a major advance against the current obesity pandemic." (PMID 36992609, 2023). "In our study, the concentrations of the GDF-15 cytokine were in the range of physiological values ​​, but after traction therapy its levels decreased in the normal-weight group of women, while increased in women with obesity." (PMID 36927409, 2023).
Obesity (continued). "Despite its central role in metabolic regulation, obesity, and other components that are part of MetS, studies investigating association between GDF15 levels and the whole MetS entity were lacking until recently." (PMID 36992609, 2023). "Elevated GDF15 serum levels have been detected in various diseases and within the orthodontic context, more relevant in obesity and aging, which may impact tooth movement in these patient groups." (PMID 37373159, 2023). "Both GDF15 and FGF21 are central endocrine regulators of systemic energy metabolism and glucose homeostasis with robust therapeutical potential for the treatment of obesity and associated metabolic diseases." (PMID 37818094, 2023). "Indeed, systemic overexpression of GDF15 prevents obesity and insulin resistance by modulating metabolic activity and enhancing the expression of thermogenic and lipolytic genes in brown adipose tissue (BAT) and white adipose tissue (WAT)." (PMID 37818094, 2023). "Adipsin, CS-846 and GDF-15 aspire to be the low back pain biomarkers in women with obesity, but there is a need for further research to answer whether they might be considered reliable biomarkers for the prognosis and monitoring of chronic low back treatment." (PMID 36927409, 2023). "Moreover, the overexpression of GDF15 promotes the lean phenotype in animals with experimental obesity and T2DM through the activation of the GFRAL receptor." (PMID 36444166, 2022). "We, therefore, recommend the range of plasma GDF15 levels for anti-obesity purposes." (PMID 35202387, 2022). "In summary, CPT ameliorates obesity by acting as a GDF15 inducer, providing a convincing argument that CPT may have therapeutic benefits for obesity and its associated metabolic disorders." (PMID 35202387, 2022). "To determine whether long-term CPT treatment could sustain high circulating levels of GDF15 and thereby alleviates obesity in mice, we performed longitudinal study in which both DIO mice and ob/ob mice orally received 1 mg kg−1 day−1 of CPT for 30 days." (PMID 35202387, 2022). "Several studies showed that GDF15 levels are increased in patients with obesity and diabetes." (PMID 35264099, 2022). "•GDF15 knockout mice display greater obesity on a high fat diet." (PMID 36064109, 2022). "It was reported that GDF15 contributed to multiple pathological processes, including inflammation, cancer, cardiovascular diseases, and obesity, and it could be applied as a biomarker of radioresistance of human fibroblast cells, oral cancer and lung cancer." (PMID 36142823, 2022). "However, GDF-15 acts more as a regulator than an inducer of obesity, as illustrated in mouse models where GDF-15 overexpression and administration of recombinant GDF-15 decrease glucose intolerance and enhance lipid metabolism." (PMID 35251002, 2022). "Thus, the aim of this work was to explore a pharmacological GDF15 inducer and test its anti-obesity efficacy in order to provide alternative anti-obesity therapeutics." (PMID 35202387, 2022). "Interestingly, increased GDF15 and FGF21 expression has been shown to exert some protective effects against various pathogenic conditions including heart failure and obesity." (PMID 35323645, 2022). "In addition, UPRmt promotes systemic energy expenditure via GDF15 that is capable of enhancing lipid consumption in muscle and adipose tissues, which in turn contributes to protecting the body from obesity." (PMID 36187475, 2022). "GDF15 has become a keen target of interest for anti-obesity therapies." (PMID 35202387, 2022). "The expression of GDF-15 mRNA was upregulated in individuals living with obesity; serum GDF-15 concentration has recently been reported as a predictor of liver fibrosis in patients with NAFLD and was involved in the association between insulin resistance and liver fibrosis." (PMID 35958557, 2022).
Obesity (continued). "However, most of the previous studies mainly focused on the function of GDF15 in obesity and cardiac metabolic diseases, and little is known about how GDF15 affects the radioresistance of cancer." (PMID 36142823, 2022). "Our results do not support GDF15 plasma levels as a causal factor at normal human plasma levels for obesity or its related cardiometabolic diseases." (PMID 35916366, 2022). "We acknowledge some limitations of our study such as not observing any direct associations between GDF-15 and obesity parameters, for instance, BMI or renal fat in our studied children." (PMID 34521901, 2021). "Gdf15 (growth/differentiation factor 15) is a distant member of the bone morphogenetic protein subfamily of the transforming growth factor‐beta, currently being investigated as a potential target for the treatment of obesity and type 1 diabetes mellitus." (PMID 33369170, 2021). "Because of the reduced lumen stenosis in BT of GDF-15−/−/ApoE−/− mice after CED, we investigated whether GDF-15 deficiency affects obesity and blood lipid concentration." (PMID 34571994, 2021). "In addition, preclinical obesity studies have shown treatment with GDF15 decreases food intake and body weight." (PMID 34777390, 2021). "The important role of lysosomes in ATM was further supported by a study in which transgenic overexpression of TFEB in macrophages triggered lysosomal biogenesis, which protected mice against HFD-induced obesity and insulin resistance with a key role for growth differentiation factor 15 (GDF15)." (PMID 33919858, 2021). "However, taking into account the ISR-induced anti-obesity effects of FGF21 in addition to GDF15, ISR enhancers represent attractive alternatives for appetite control in patients with metabolic disorders." (PMID 34877504, 2021). "Additionally, we showed in a previous study that GDF15, another mitokine, can be induced by Th2 cytokines/STAT6 signaling, thereby preventing metabolic impairment caused by obesity and insulin resistance." (PMID 34073755, 2021). "Serum level of GDF-15 is closely related to many diseases, including inflammation, cancer, cardiovascular disease and obesity, thus, GDF-15 could be used as a reliable predictor of disease progression." (PMID 33638948, 2021). "Further research studies may help disclose whether GDF-15 treatment can limit the pro-inflammatory effects of IgA and IgG in obesity." (PMID 34521901, 2021). "Akin to leptin resistance in obesity, increased FGF21 and GDF15 levels in obesity might indicate resistance to these cytokines, and a concomitant decrease in function, though this remains unresolved." (PMID 34777390, 2021). "Our findings may also have implications for the development of GDF15 agonists as therapeutics for obesity and related metabolic disorders." (PMID 34187898, 2021). "Ultimately, clinical studies would be required to determine whether nausea is contraindicative for GDF15 as an obesity therapeutic." (PMID 33903632, 2021). "Given that GDF15 is upregulated in obesity and that GDF15 can exert an anorectic action, it seems possible that GDF15 may be able to provide a regulatory brake on appetite and weight gain in states of chronic overnutrition." (PMID 32310257, 2020). "Further work is needed to determine if GDF15 expression is meant as a protective measure to limit the impact of stress on the organism as suggested by others, perhaps by limiting the inflammatory milieu observed during obesity." (PMID 32671100, 2020). "In addition to those different ER stress stimuli known to promote GDF15 expression, SFAs represent interesting pathophysiological stimuli linking obesity and GDF-15." (PMID 33302552, 2020). "Obesity increases GDF15 expression in liver and adipose tissue." (PMID 33302552, 2020). "Thus, GDF15 clearly has a role in metabolic adaptation and acts potentially as a regulator of phenotypes of obesity that require further investigation." (PMID 32671100, 2020).